TMEM185B (transmembrane protein 185B)
Synonyms: FAM11B; FLJ20979
Tractability: Antibody: UniProt predicts a signal peptide or a membrane-spanning region. PROTAC: ubiquitination databases record sites on it.
Gene: Protein-coding gene on chromosome 2 (120,217,479 to 120,223,400, reverse strand). Ensembl gene ENSG00000226479.
Subcellular location: Membrane
Subcellular location (Human Protein Atlas): Endoplasmic reticulum
Gene Ontology:
Cellular component: membrane
Genetic constraint (gnomAD): Loss-of-function variants: 9 observed, 20.28 expected, observed/expected ratio (o/e) 0.44, 90% interval 0.27 to 0.77. The upper end of that interval is the gene's LOEUF score, 0.77, which puts it in group 3 of 6, group 1 being the genes least tolerant of losing a copy. Missense variants: 392 observed, 417.96 expected, observed/expected ratio (o/e) 0.94, 90% interval 0.86 to 1.02. Synonymous variants: 204 observed, 170.28 expected, observed/expected ratio (o/e) 1.2, 90% interval 1.07 to 1.35.
Homologues: Orthologues: macaque TMEM185B (99% identical), dog TMEM185B (97% identical), pig TMEM185B (97% identical), rat Tmem185b (96% identical), mouse Tmem185b (96% identical), chimpanzee TMEM185B (79% identical), rabbit TMEM185B (75% identical), Drosophila melanogaster CG14194 (47% identical), Caenorhabditis elegans Y116A8C.9 (38% identical). Paralogues in human: TMEM185A (88% identical), TMEM60 (11% identical).
Diseases named in the same sentence as TMEM185B in open-access papers:
TMEM185B is named in the same sentence as 2 diseases in open-access papers, as found by Europe PMC text mining. Sharing a sentence is not in itself a finding about the gene and the disease.
TMEM185B shares sentences with these, for which no sentence is quoted: endometrial cancer (1 paper); glioblastoma (1).